CTLA4 (cytotoxic T-lymphocyte associated protein 4)
Diseases named in the same sentence as CTLA4 in open-access papers (continued):
Sharing a sentence is not in itself a finding about the gene and the disease.
cancer (continued). "Cancer immunotherapy has witnessed a revolution in the past decade with the development of immune checkpoint inhibitors (ICIs), monoclonal antibodies against cytotoxic T lymphocyte antigen 4 (CTLA-4) and programmed cell death protein 1 (PD-1) or their ligands, such as PD1 ligand 1 (PD-L1)." (PMID 29970158, 2018). "One can hypothesize that different responses to checkpoint inhibitor therapy could be a consequence of heterogeneous intra- and inter-tumor expression of different kinds of checkpoints, though data on the expression status of ILTs and CTLA-4 and PD-L1 in cancers are rather limited." (PMID 30319626, 2018). "Thus, the immunomodulatory nature of VA raises the question of whether there are immunologic interactions between VA and inhibitors of the PD-1/PDL-1 or CTLA-4 pathways that might lead to increased toxicity for cancer patients." (PMID 29237435, 2017). "In addition, we evaluated the influence of each study on the overall meta-analysis estimate by sensitivity analysis, which indicated that all data correlated with prognostic role of CTLA-4 expressions in all cancer patients were stable with OS as the endpoint in our analysis." (PMID 28211499, 2017). "Similarly, Bacteroides thetaiotamicron and nontoxigenic B. fragilis improve the efficacy of an anti–cytotoxic T-lymphocyte-associated protein 4 (CTLA4) immunotherapeutic tested in 3 cancer xenograft mouse models." (PMID 28934351, 2017). "Recently, antibodies to two co-inhibitory receptors, CTLA-4 and PD-1, called immune checkpoint blocking antibodies, have attracted attention as novel therapeutic drugs, since they exhibit remarkable clinical efficacy for patients with various cancers by reinvigorating exhausted CD8+ T cells." (PMID 26735971, 2016). "Consistent with a pivotal role for CD80 in cancer immune surveillance, blocking CD80 signaling caused a significant increase in HGD frequency and extension (p = 0.01 and p = 0.04, respectively), whereas the number and total area of HGD foci were minimal in anti-CTLA4-treated mice." (PMID 25595911, 2015). "However, in cancer patients, there are multiple self antigens for which the maintenance mechanisms of self tolerance can be disrupted with anti-CTLA-4 therapy at varying doses and intervals, resulting in unpredictable manifestations of 20–60% of irAEs with grade 1–4 severity." (PMID 24904570, 2014). "A cancer vaccine that produces a meager antitumor response in vivo could have enhanced efficacy when administered alongside a treatment that elicits global T cell activation, such as CTLA4 blockade." (PMID 24672527, 2014). "Polymorphisms in CTLA-4 are regarded as genetic susceptibility factors; however, there are reports that could not establish any associations between different CTLA-4 SNPs and several types of cancers." (PMID 23936819, 2013). "Additionally, we were interested in the question of whether the distribution of CTLA-4 genotypes was the same in the blood and the corresponding cancer tissue." (PMID 23936819, 2013). "For CTLA-4 60G/A polymorphism, a total of 18 studies, comprising 5571 cases and 5567 controls, our meta-analysis on the available studies suggested no significant increased cancer risk in all of the genetic comparison models." (PMID 24376736, 2013). "Moreover, they also suggest that CTLA-4 blockade may be a vital adjuvant for a 4-1BBL-expressing vaccine used to treat cancers." (PMID 22312406, 2012). "In addition, a safe means of vaccinating against prostate (or other) cancers may serve in a synergistic manner with other immune-stimulating agents, such as CTLA4-Ig, which are showing promise in combined immunotherapies in prostate and other cancers." (PMID 20824184, 2010). "When comparing PeCa patients and cancer-free controls, four inhibitory sICs (IDO, TIM-3, CD80, and CTLA-4) were found at significantly higher levels in the PeCa group." (PMID 41705256, 2026).
cancer (continued). "Cancer patients with high DLEC1 expression showed improved overall and progression-free survival under immune checkpoint inhibitor therapies, such as anti-CTLA4, anti-PD1 and anti-PDL1." (PMID 42002658, 2026). "CTLA-4 is mainly expressed by CD4+ and CD8+ T cells, as well as Tregs, and to a lesser extent by B cells, innate lymphoid cells, DCs, and cancer cells." (PMID 41486149, 2026). "As one of our primary goals was to investigate the potential importance of ICRs in γδ T cell subsets in health and in cancer, we additionally assessed expression of PD-1, TIM-3, LAG-3, TIGIT and CTLA-4 by flow cytometry in all patients." (PMID 41310392, 2026). "KIRC also shows the highest level of T-cell exhaustion, indicated by increased activity of immune checkpoint molecules like FASLG, CTLA4, PDL1, PD1, LAG3, and TIM3, which are involved in immune suppression in cancer." (PMID 40649942, 2025). "Among 60 ICP genes, including 24 immune inhibitors (such as CTLA4, LAG3, or VEGFB) and 36 activators (TNFRSF9, CD28, or TNFRSF9, etc.), we found DHCR7 played roles both in inhibitors and activators of ICP in human cancers." (PMID 41198144, 2025). "The benefits of blocking the expression of ICs such as CTLA-4 and PD, along with their ligands (CD80/86 and PD-L1/2, respectively) in cancer have been extensively investigated." (PMID 40143377, 2025). "Ipilimumab, a CTLA‐4 mAb, was the first ICI approved for cancer treatment, enhancing T cell activation and inducing lasting responses in metastatic melanoma patients." (PMID 40415479, 2025). "In cancer immunotherapy, PD-1 blockade predominantly enhances CD8+ T cell responses, whereas CTLA-4 inhibition primarily affects CD4+ T cells." (PMID 40303350, 2025). "Search terms included the following: "immunotherapy", "cancer biomarkers", "PD-L1", "MSI", "CTLA-4", "TILs", "HER2", "LDH", "S100B", "ctDNA", "TMB", "eosinophils", and "multi-omics"." (PMID 40717879, 2025). "We examined the relationship between EIF5A2 and immune checkpoints using Spearman analysis and found that EIF5A2 was correlated with CD274, PDCD1LG2, and HAVCR2 in the majority of cancers and PDCD1, CTLA4, LAG3, SIGLEC15, and TIGIT in some tumors." (PMID 40964657, 2025). "HD-PTP recruits USP8 to deubiquitylate CTLA-4 in cancer cell lines, mouse CD4-positive T cells and cancer cell-derived exosomes." (PMID 41031910, 2025). "The B7/CD28 family of molecules, comprising several immune checkpoint proteins and their receptors, such as CD28, CTLA4, PDCD1, etc. have gained considerable attention in the field of cancer therapy." (PMID 40808941, 2025). "Clinical studies have demonstrated significant effects of CTLA-4 blockade, resulting in improved overall and progression-free survival in NSCLC and other cancers." (PMID 40963596, 2025). "Further analyses showed that these high HLA‐DR+ cancer cell tumors exhibited elevated levels of LAG3, TNFRSF9, CTLA4, PDCD1, TIGIT, ITGB2, and GZMB." (PMID 40464412, 2025). "This family has transformed cancer therapy through the advent of ICI targeting PD-1, its ligand PD-L1 (B7-H1), and CTLA-4." (PMID 40508202, 2025). "Olsenella species have been shown to enhance the efficacy of anti‐CTLA‐4 treatment and boost the activation of CD4+ and CD8+ T cells in four mouse models of cancer." (PMID 40351363, 2025). "As described in previous sections, recent studies have shown that PD‐L1 and CTLA4 disrupt the effector function of CTLs, leading to the development of ICI, in which antibodies target these suppressive molecules, as a novel anti‐cancer treatment." (PMID 40257446, 2025). "Immune checkpoint inhibitors (ICIs) targeting PD-1 (CD279), PD-L1 (CD274), or CTLA-4 (CD152) have revolutionized cancer immunotherapy, leading to significant survival benefits in multiple cancer types." (PMID 41023441, 2025).
cancer (continued). "While PD-L1 inhibitors dominate HCC immunotherapy, CTLA-4 inhibitors demonstrate robust antitumor activity, particularly in advanced HCC and other cancers, offering a promising approach for improving clinical outcomes through synergistic immune modulation." (PMID 40317077, 2025). "ICIs are a key focus in cancer research, blocking tumors by reactivating immune cells through targeting checkpoints like PD1/PD-L1 and CTLA4." (PMID 40928500, 2025). "The correlation between SLC2A1 expression and eight immune checkpoints (CTLA4, PDCD1, TIGIT, LAG3, CD274, HAVCR2, PDCD1LG2, and SIGLEC15) was further investigated across multiple cancer types." (PMID 40824962, 2025). "Our research shows that PIEZO1 expression is positively correlated with key immune checkpoints, including CD274 (PD-L1), CTLA4, LAG3, PDCD1 (PD-1), PDCD1LG2 (PD-L2), and TIGIT across various cancer types." (PMID 40977743, 2025). "Cancer cells often evade immune surveillance by exploiting immune checkpoint receptors, such as TIM-3, LAG-3, CTLA-4, and PD-1." (PMID 40870970, 2025). "To further explore the potential of ELFN1 as a target for cancer immunotherapy, we analyzed the OS of patients with high or low ELFN1 expression who received anti-PD1, anti-PDL1, or anti-CTLA4 therapy." (PMID 41357574, 2025). "Eosinophils are expected to be of use as cellular biomarkers and effector cells in cancer therapy following ICI, especially with anti-CTLA4 and anti-PD-1 antibodies." (PMID 40920775, 2025). "The CTLA-4 mAb binds specifically to CTLA-4 and prevents CTLA-4 from binding to B7, thereby blocking the CTLA-4 pathway and activating T-lymphocytes to kill cancer cells." (PMID 39923010, 2025). "Anti-PD-1/PD-L1 and anti-cytotoxic T-lymphocyte antigen 4 (CTLA-4) treatments have shown success and have been FDA-approved for several cancer types." (PMID 41463203, 2025). "This accumulating evidence underscores the potential synergistic effects of combining immunotherapeutic agents, notably anti-PD-1 and anti-CTLA-4, in conjunction with PEM, opening new avenues for the advancement of cancer treatment modalities." (PMID 41237182, 2025). "The use of antibodies against PD‐1, CTLA4, and TIGIT has been tested in clinical trials for treating cancer patients." (PMID 40100045, 2025). "Moreover, antibodies targeting the immune checkpoint molecules PD-1, PD-L1, and cytotoxic T-lymphocyte antigen 4 (CTLA-4), administered alone or in combination with chemotherapy, are the standard of care in most patients with metastatic non-small cell lung cancers and other cancers." (PMID 40732268, 2025). "Interestingly, there are reports of C-terminal CTLA-4 variants associated with cancer but not CHAI." (PMID 41608053, 2025). "In 1996, Allison and his colleagues demonstrated through animal models that inhibitory antibodies that block CTLA-4 can boost the immune response against tumors, marking the first successful application of CTLA-4 in cancer treatment." (PMID 40918452, 2025). "Ipilimumab, a humanized CTLA-4 monoclonal antibody, was the first ICI approved by the FDA and remains a cornerstone of cancer immunotherapy, particularly for unresectable/metastatic melanoma and metastatic esophageal squamous cell carcinoma." (PMID 40561796, 2025). "Curcumin exerts immunomodulatory effects by modulating various immune checkpoints (PD-1, CTLA-4, and CD47, and PD-L2) facilitating the recognition and elimination of cancer cells by immune cells." (PMID 40490812, 2025). "Clinically, ICIs such as anti-CTLA-4, anti-PD-1, PD-L1, and the novel immune checkpoint inhibitor LAG-3 have demonstrated efficacy across various cancer types, resulting in improved patient outcomes." (PMID 40373023, 2025). "Collectively, ICI therapy targeting PD-1/PD-L1, CTLA-4, LAG-3, TIM-3, TIGIT, and VISTA has advanced cancer immunotherapy, with combinations and BsAbs augmenting efficacy." (PMID 41239350, 2025).
cancer (continued). "One is the breakdown of immune tolerance to the heart mediated by the CTLA-4, PD-1, and LAG-3 pathways, and the other involves the expansion of T cells targeting a common antigen shared by the cancer and the heart." (PMID 40547024, 2025). "CTLA-4 is an inhibitory molecule that competes with the co-stimulatory molecule CD28 for binding, thereby regulating T-cell responses against pathogens and cancer." (PMID 40143377, 2025). "The approval of ipilimumab, a CTLA-4 inhibitor, marks a significant milestone in this field, underscoring the potential of ICB to improve patient outcomes across various cancer types." (PMID 41431699, 2025). "Interestingly, our network-based analysis recognized the interactions between IFNG and the effector PTPs activated by PD-1 and CTLA4 signaling as a potential hub through which the effects of ICI cancer treatment could lead to the observed differences between irMyositis and DM38." (PMID 40759686, 2025). "Antigen-presenting molecules like MHC-I, MHC-II, co-inhibitory molecules (CTLA4), or co-stimulatory molecules (CD80, CD86) are crucial for presenting cancer antigens to T cells and triggering an immune reaction." (PMID 39980072, 2025). "The expression level of TIM3, CTLA‐4, and PD‐1 was also significantly enriched in most T‐cell subpopulations in MSI‐like cancers compared to other MSS patients." (PMID 40181205, 2025). "In vitro, anti-CTLA-4 antibody activates EGFR pathway in CTLA-4 expressing cancer cells, induces cell proliferation as well as the expression of PDL-1 in the cancer cells." (PMID 40109334, 2025). "While anti-CTLA4 and anti-PD1 are standard treatments for many solid tumors, TIGIT and LAG3 have emerged as promising new targets for cancer immunotherapy." (PMID 40067762, 2025). "In the adjusted model for hospitalization‐free survival for both NLR and albumin, CTLA‐4 checkpoint therapy, ECOG > 0 and cancer stage IV were the significant predictors of hospitalization." (PMID 39817619, 2025). "CTLA-4 exhibits higher affinity for B7 ligands than CD28, suppressing T cell activation and limiting anti-cancer immune responses." (PMID 40872476, 2025). "In the presence of immune checkpoint inhibitors targeting the CTLA-4/CD80 and PD-1/PDL-1 signaling pathways, these pathways are inhibited, and T cells are reactivated, leading to the death of cancer cells." (PMID 41357573, 2025). "FoxP3 is a key transcription factor regulating the expression of several genes required for important Treg functions, such as CD25, CTLA4, CD73, and CD39, suggesting it as a potential target for cancer immunotherapy." (PMID 40034859, 2025). "Recent research has demonstrated the effectiveness of combining anti-CTLA-4 and anti-PDL-1 treatments for advanced cancers." (PMID 39359534, 2024). "The findings from this study strongly suggest that considering CTLA-4 as a prospective biomarker could prove valuable in diagnosing OC while highlighting that elevated concentrations of PD-L1 and PD-1 serve as unfavorable prognostic indicators for this particular form of cancer." (PMID 38903506, 2024). "Evidence supports that ICAM1 binds to MUC1, which is known to be overexpressed in cancer cells and cancer stem cells, and CD80 binds to CTLA4, which is an immunosuppressive marker that is also expressed in cancer stem cells." (PMID 38903193, 2024). "MEDALLION is a non-randomised longitudinal cohort study aiming to recruit 66 cancer patient recipients of anti-PD1/PD-L1, anti-CTLA-4 or combination therapy." (PMID 38877461, 2024). "Our findings revealed that cancer patients with higher IL-2RG expression derive greater benefits from immunotherapies involving anti-PD1, anti-PD-L1, and anti-CTLA-4 treatments." (PMID 38720389, 2024). "Then, immune checkpoints analysis shown that UBE2C had a negative correlation with immune checkpoints, such as CD274(PD-1), PDCD1(PD-L1), CTLA4, TIGIT, LAG3, HAVCR2, and PDCD1LG2 in a great many cancers." (PMID 38370368, 2024).
cancer (continued). "In the past two decades, emerging studies confirmed that the blockade of ICBs (PD-1, PD-L1, CTLA4, TIM-3, TIGIT etc.)has rapidly become the most promising anti-cancer strategies for multiple types of cancer, including GC." (PMID 39074262, 2024). "Other receptors, such as CTLA-4, TIM-3, TIGIT, and CD96, should be studied more thoroughly for their potential clinical targeting for cancer immunotherapies." (PMID 39339180, 2024). "In this case, anti-CTLA-4 and anti-TIGIT therapies not only led to a reduction in the percentage of mesenchymal EpCAM− cancer cells but also induced the enrichment of epithelial EpCAM+ cancer cells." (PMID 38914547, 2024). "According to the literature, CTLA4 with a higher binding affinity to CD80 delivers inhibitory signals for activation of T lymphocytes and immune responses against malignant tumors." (PMID 39081321, 2024). "These nuclides when attached to nanobodies are particularly useful for imaging cancer biomarkers like HER2,131 HER3,132 and EGFR,133 as well as immune checkpoints such as PD‐L1134 and CTLA‐4,135 and the tumor microenvironment." (PMID 39166870, 2024). "By blocking the function of CTLA-4, CTLA-4 inhibitors can inhibit T-cell activation, thereby improving the capacity of the immune system to recognize and attack cancer cells." (PMID 38903506, 2024). "Although the CTLA-4 isoforms are mostly known to be T cell derived, many human cancer cell types express both CTLA-4 transcripts and functional CTLA-4, detectable in the cytoplasm or on the cell surface." (PMID 38053333, 2024). "Nevertheless, despite the remarkable efficacy of CTLA-4 and PD1-PDL1(programmed cell death 1 ligand 1)-targeted therapies in cancer immunotherapy, a significant proportion of patients exhibit a restricted response to these treatments." (PMID 38390331, 2024). "Cancer treatment has been revolutionized by introducing Immune Checkpoint receptors inhibitors (ICR), such as anti-CTLA4, anti-PD-1, and anti-PD-L1.3." (PMID 39092051, 2024). "In 2018, two immunologists, Hojo and Allison, received the Nobel Prize in Physiology or Medicine for their discovery of cancer therapy by inhibition of negative regulation of PD1 and CTLA-4, respectively." (PMID 38539487, 2024). "There are at least 11 bsAbs targeting CD19 × CD3, EGFR × MET, gp100 × CD3, CD20 × CD3, BCMA × CD3, CTLA-4 × PD-1, CD20 × CD3, and GPRC5D × CD3, which have been approved for treatment of various cancers." (PMID 38257366, 2024). "Due to their ability to significantly improve patient survival, therapeutic monoclonal antibodies targeting CTLA-4 and PD-1/PD-L1 have been approved by the United States Food and Drug Administration (FDA) for the treatment of a range of cancers." (PMID 38328418, 2024). "In pan-cancer, high expression of HTR1B/1F/2B/4/7 was positively correlated with the expression of PD-1, PD-L1, and CTLA4 while the expression of HTR1A was negatively correlated with the expression of PD-1, PD-L1, and CTLA4 in GLB, LGG, SARC, OV, and PAAD." (PMID 39766808, 2024). "Given anti-CTLA-4 as a well-established ICB therapy, these findings raise a possibility of DCs mediating anti-CTLA-4 effects in vivo and validate the targeting of CTLA-4 on DCs to enhance ICB efficacy-in cancers." (PMID 38261139, 2024). "Anti-CTLA4, anti-PD1, and anti-PDL1 therapy have achieved robust success across multiple cancer types, including melanoma, non-small-cell lung cancer (NSCLC), and colorectal cancer." (PMID 39199612, 2024). "Compared with the low-CAPS group, the high-CAPS group had a pro-cancer immune microenvironment, low TMB, high TIDE score, and relatively poor anti-PD-1 and anti-CTLA4 therapeutic efficacy." (PMID 39040110, 2024). "In conclusion, the dual-targeting immunotherapy utilizing aptamers against CTLA-4 and NKG2A presents a promising approach for cancer treatment." (PMID 38473398, 2024).